ZNF654 (zinc finger protein 654)
Description:
May be involved in transcriptional regulation.
Synonyms: FLJ10997; FLJ21142
Tractability: PROTAC: ubiquitination databases record sites on it.
Gene: Protein-coding gene on chromosome 3 (88,058,723 to 88,144,662, forward strand). Ensembl gene ENSG00000175105.
Subcellular location: Nucleus
Subcellular location (Human Protein Atlas): Microtubules; Cytokinetic bridge; Mitotic spindle; Nucleoplasm
Gene Ontology:
Molecular function: DNA binding; DNA-binding transcription factor activity; DNA-binding transcription factor activity, RNA polymerase II-specific
Biological process: regulation of transcription by RNA polymerase II
Cellular component: nucleus
Genetic constraint (gnomAD): Loss-of-function variants: 13 observed, 67.73 expected, observed/expected ratio (o/e) 0.19, 90% interval 0.12 to 0.31. The upper end of that interval is the gene's LOEUF score, 0.31, which puts it in group 1 of 6, group 1 being the genes least tolerant of losing a copy. Missense variants: 845 observed, 1,060.9 expected, observed/expected ratio (o/e) 0.8, 90% interval 0.75 to 0.84. Synonymous variants: 320 observed, 358.61 expected, observed/expected ratio (o/e) 0.89, 90% interval 0.81 to 0.98.
Homologues: Orthologues: chimpanzee ZNF654 (99% identical), macaque ZNF654 (99% identical), pig ZNF654 (93% identical), rabbit ZNF654 (90% identical), mouse Zfp654 (88% identical), rat Zfp654 (87% identical), guinea pig ZNF654 (85% identical), tropical clawed frog znf654 (49% identical), zebrafish znf654 (33% identical). Paralogues in human: ZNF292 (26% identical), RLF (23% identical).
Diseases named in the same sentence as ZNF654 in open-access papers:
ZNF654 is named in the same sentence as 1 disease in open-access papers, as found by Europe PMC text mining. Sharing a sentence is not in itself a finding about the gene and the disease. The quoted sentences say what the papers report.
prostate carcinoma (1 paper, 2022). A carcinoma that arises from epithelial cells of the prostate gland. "The HPA database suggested that C18orf25, DYNC1LI2, SYNJ1, MAPK1, and ARID4B are highly expressed in normal tissues, and CLOCK, SETD2, ZNF654, XIAP, MIS18BP1, and MBTPS2 are highly expressed in prostate cancer tissues." (PMID 36249009, 2022).